AURKB (aurora kinase B)
Diseases named in the same sentence as AURKB in open-access papers (continued):
Sharing a sentence is not in itself a finding about the gene and the disease.
oesophageal cancer (1 paper, 2020). "We analysed the correlation of AURKA or AURKB with BRD4 in oesophageal cancer using the GEPIA web‐based tool." (PMID 32954665, 2020). "Together, our data suggested that BRD4 inhibition induced cellular senescence by down‐regulating AURKA and AURKB in human oesophageal cancer cells." (PMID 32954665, 2020). "Finally, using the TCGA database, we determined that the expression of AURKA and AURKB in oesophageal cancer tissues is much higher than those in the normal tissues." (PMID 32954665, 2020). "In conclusion, our study explored the anti‐proliferative effect of JQ1 in oesophageal cancer cells and identified the regulatory mechanism involved in their senescence through the up‐regulation of p21 and down‐regulation of AURKA and AURKB." (PMID 32954665, 2020).
ovarian serous carcinoma (1 paper, 2017). "For example, BUB1 mRNA was significantly co-expressed with AURKB mRNA in advanced-stage ovarian serous carcinoma." (PMID 28427189, 2017).
prostatic intraepithelial neoplasia (1 paper, 2024). "Nuclear localization of AURKB in prostatic intraepithelial neoplasia lesions is associated with clinical staging." (PMID 38877472, 2024).
skin carcinoma (1 paper, 2012). "Using the Oncomine database, the analysis of the transcriptome of human cell lines and xenografts with sensitivity to drugs designed against AURKA, AURKB or PLK1 kinases show a profile similar to that seen in the described mouse skin carcinomas." (PMID 22880004, 2012).
spinocerebellar ataxia type 10 (1 paper, 2024). Spinocerebellar ataxia type 10 (SCA10) is a subtype of type I autosomal dominant cerebellar ataxia (ADCA type I). "Notably, AURKB has been implicated in another autosomal dominant neurological disorder, spinocerebellar ataxia type 10 (SCA10), characterized by cerebellar dysfunction and varying degrees of signs from other components of the CNS." (PMID 38534384, 2024).
Thrombocytopenia (1 paper, 2025). A reduction in the number of circulating thrombocytes. "We therefore hypothesized that megakaryocyte progenitors in subsets of MDS patients with thrombocytopenia would elevate expression levels of mitotic genes, including AURKA, AURKB, and PLK1, which in turn would promote cytokinesis/cell cycling rather than endomitosis." (PMID 40813622, 2025).
cancer (314 papers, 2004 to 2026). A tumor composed of atypical neoplastic, often pleomorphic cells that invade other tissues. "We have observed that this cancer hallmark is enriched in the most resistant OS subtype S1 which exhibits overexpression of the AURK family member AURKB." (PMID 40427174, 2025). "Some studies have also shown that miRNAs can specifically target AURKB and are associated with drug resistance in cancers." (PMID 39787178, 2025). "The abnormal expression of AURKB was associated with pathogenesis and drug resistance in a variety of cancers." (PMID 40427174, 2025). "Aberrant AURKB expression is frequently observed in various cancers, where it is associated with chromosomal instability and increased malignancy." (PMID 40710353, 2025). "The overexpression of AURKB has been shown to cause aneuploidy and chromosome instability in vitro in various cancer types." (PMID 40149290, 2025). "Previous studies revealed that AURKB is overexpressed in various human cancers, and high expression of AURKB is associated with a poorly differentiated phenotype, enhancing cell proliferation, and lymph node metastasis." (PMID 39927464, 2025). "AURKB deregulation has been detected in various cancers, and its overexpression is commonly associated with tumor cell invasion, metastasis, and drug resistance." (PMID 39787178, 2025). "The activation of AURKA and AURKB has been shown to play an important role in multiple cancers, and their overexpression is generally associated with tumor cell invasion and metastasis." (PMID 39045407, 2024). "Nevertheless, a more exhaustive examination of the molecular mechanisms underlying AURKB's role is essential for the development of innovative pathways in cancer diagnosis and therapeutic research." (PMID 38898693, 2024). "First, PCPs can improve their ability to make early diagnosis and prognostic assessment of patients by understanding the high level of expression of AURKB genes and proteins in a variety of cancers and their association with poor prognosis." (PMID 38898693, 2024). "Survival analysis showed that AURKB was associated with overall survival in 12 cancer types and progression‐free survival in 11 cancer types." (PMID 38898693, 2024). "Overexpression of AURKA and AURKB has been observed in various cancers, including NSCLC, and is associated with poor prognosis and drug resistance." (PMID 38600056, 2024). "In an examination of the relationship between AURKB expression and the prognosis of specific cancer types, a risk prediction model for OS in KIRC was developed." (PMID 38898693, 2024). "AURKB is often overexpressed in human malignancy and elevated AURKB is associated with high histologic grade and unfavorable outcome in different types of cancers." (PMID 37903144, 2023). "This compound displayed substantial cytotoxic activity in several cancer cell lines and promoted the loss of function in Aurora Kinase B (AURKB) phenotypes." (PMID 37631072, 2023). "Although AURKB had been thought to be a tumor suppressor gene, some studies have found that the upregulation of AURKB is a risk factor for cancer development." (PMID 34593983, 2023). "Because of the association between increased expression of AURKB in several different cancer types and poor prognosis, several AURKB inhibitors are being tested in clinical trials." (PMID 35853811, 2022). "We observed a high number of K63-linked polyubiquitinated AURKB molecules in all three cancer types compared with normal tissues." (PMID 35853811, 2022). "Further, it was shown that RASSF7 downregulation leads to a loss of AURKB activation in cancer cells." (PMID 33915740, 2021).
cancer (continued). "Overexpression and enhanced kinase activity of AURKB in various tumour types are well documented and associated with therapy resistance and low survival rate in various cancers." (PMID 32811973, 2021). "It is well‐documented that overexpression of AURKB in numerous cancer types causes uncontrollable tumor cell proliferation and helps in evading apoptotic death." (PMID 32761869, 2020). "Among the ZNF143-targeted cell cycle-associated kinases, both PLK1 and Aurora kinase B (AUPKB) were overexpressed in a large variety of cancers." (PMID 32076462, 2020). "Both AURKA and AURKB are implicated in tumour resistance pathways for selective EGFR inhibitors in cancer." (PMID 29115879, 2018). "In CRC, overexpression of AURKA is associated with CIN, while AURKB correlates with advanced stages and a worse patient outcome in many cancer types." (PMID 23110075, 2012). "It has been shown that increased levels of AURKB cause genetic instability and cancer due to spindle checkpoint anomalies and polyploidization, however, the low levels of AURKB detected in this report indicate a minor role for this kinase in TGCT." (PMID 20411023, 2010). "AURKB's expression indicated a positive diagnostic significance for multiple cancer types." (PMID 38898693, 2024). "However, the upstream regulatory mechanisms underlying the AURKB oncogenic activity in cancer cells remain poorly understood." (PMID 38233848, 2024). "In this study, we determined that AURKB is widely overexpressed in cancer and is significantly associated with poorer prognosis in cancer patients, and can be used as a diagnostic and prognostic marker for a variety of cancers." (PMID 38898693, 2024). "As cancer-associated kinases, both AURKA and AURKB have been extensively studied in search for new potential small molecular inhibitors that could be used in anti-cancer therapy (reviewed by Borisa and Bhatt)." (PMID 33572108, 2021). "Therefore, both AURKA and AURKB appear to be associated with malignant phenotypes of cancer and function as oncogenes." (PMID 27636990, 2016). "Indeed, negligible cancer-associated mutations are reported for Aurora kinase B, Cdk1, Cyclin B, Nek2, and Pin1, proteins involved in initial events of mitosis." (PMID 25999914, 2015). "Also, SETD1 methylation of HSP70 on K561 promotes the association of the chaperone to Aurora Kinase B and stimulates the proliferation of cancer cells." (PMID 24714364, 2014). "Furthermore, our investigation delved into the miRNA‐AURKB regulatory network, uncovering the potential utility of AURKB as a diagnostic, prognostic and predictive target for anti‐cancer therapy across various types of cancer." (PMID 38898693, 2024). "For example, AURKB can promote cancer proliferation by inducing epithelial-mesenchymal transition through the PI3K/AKT signaling cascade." (PMID 40059874, 2025). "Cory has been shown to induce cancer cell death by inhibiting Aurora kinase B activity, leading to centrosome clustering defects and mitotic arrest." (PMID 41233831, 2025). "Aurora kinase B inhibitors, such as Barasertib, have shown promise in clinical trials, reducing tumor growth and delaying relapse in patients with advanced cancers." (PMID 40634321, 2025). "Although AURKB has long been recognized as a pan-cancer therapeutic target, the clinical efficacy of AURKB inhibitors has remained disappointing, raising concerns regarding non-classical, kinase-independent carcinogenic mechanisms." (PMID 40784984, 2025). "In contrast, the knockdown of the AURKB gene resulted in the inhibition of cancer cell proliferation by arresting the cell cycle in the G2/M phase." (PMID 40005158, 2025).
cancer (continued). "The protein AURKB plays a significant role in controlling various signaling pathways that impact the growth, survival, invasion, mobility, and apoptosis of cancer cells." (PMID 40059874, 2025). "The Aurora kinase family, which includes AURKA, AURKB, and AURKC, has been implicated in various cancers, with overexpression linked to chromosomal amplification of the AURKA gene." (PMID 40564876, 2025). "Another key oncogene, AURKB, is widely recognized as a therapeutic target across multiple cancer types." (PMID 40710353, 2025). "Targeting AURKB is increasingly recognized as a hopeful strategy for treating multiple cancer types." (PMID 40059874, 2025). "Later, functional studies conducted with MCF-10A, MCF-7, and MDA-MB-231 cell lines demonstrated that let-7b-5p inhibits cancer cells through AURKB and sensitizes them to Dox resistance." (PMID 39787178, 2025). "Recent studies suggest that HATs and histone deacetylases (HDACs) modulate AURKB function in cancer." (PMID 40710353, 2025). "Overexpressed AURKB is common in pro-tumorigenic pathways involved in many cancer types, including lung, prostate, breast and liver." (PMID 41357898, 2025). "Both proteins have been previously targeted in human cancers, with multiple AURKB and PLK1 inhibitors gaining FDA approval." (PMID 40149290, 2025). "Aurora kinase B (AURKB) targeting bypasses the effect of RB mutations, thereby restoring the anti-cancer effect of tazemetostat." (PMID 40968252, 2025). "The results showed that AURKB protein expression was mainly located in the nucleus, and the expression level of its protein was higher in cancer tissues (Tumour vs Normal = 21/50 versus 7/50, p = 0.002)." (PMID 38898693, 2024). "Within these 11 malignancies, elevated AURKB expression was strongly correlated with a reduction in DSS." (PMID 38898693, 2024). "Thirty-three cancer datasets acquired from the TCGA database were analyzed for AURKB expression in both tumor and normal tissues." (PMID 38396874, 2024). "Currently, some small-molecule drugs targeting AURKA and AURKB have been discovered for cancer treatment." (PMID 39045407, 2024). "AURKB has a potential impact on cancer progression through its effects on cell cycle regulation as well as inflammatory and immune‐related pathways." (PMID 38898693, 2024). "Similar to AURKB, MAD2L2 is dysregulated in different cancer cell lines and tumor tissues; MAD2L2 overexpression is associated with poor prognosis in various cancer types." (PMID 38515112, 2024). "As compared to normal tissues, AURKB was dramatically up-regulated in 18 cancer tissues, including HCC, except for cancers with missing or too few normal tissue samples." (PMID 38396874, 2024). "A decrease in the methylation of AURKB has been observed across multiple cancer types, illustrating a critical link between this gene and malignant transformations." (PMID 38898693, 2024). "The results show that AURKB is highly expressed in most cancers, and the protein level of AURKB and the methylation level of its promoter vary among cancer types." (PMID 38898693, 2024). "Aurora kinase B (AURKB), an essential regulator in the process of mitosis, has been revealed through various studies to have a significant role in cancer development and progression." (PMID 38898693, 2024). "Both AURKA and AURKB are known to be upregulated in many cancers and their expression has been shown to be regulated by the EWSR1/FLI1 fusion." (PMID 39518006, 2024). "While AURKB demonstrated an inverse association with immunomodulatory genes in YHM, LUAD, ESCA, LUSC, TGCT and GBM, other cancers exhibited minimal or statistically insignificant connections with regulatory genes." (PMID 38898693, 2024). "Mitotic kinases such as AURKA and AURKB have gained much attention as potential therapeutic targets against cancer, due to their essential role in the cell cycle, especially during mitosis." (PMID 38886738, 2024).
cancer (continued). "Currently, some small-molecule drugs targeting AURKA and AURKB have been discovered for the treatment of cancer." (PMID 39045407, 2024). "AURKB was found to be ubiquitously and significantly overexpressed in cancer tissues based on data from the TCGA database and the GEO database." (PMID 38396874, 2024). "Previous studies have demonstrated that AURKB promoted cancer progression through various mechanism." (PMID 38713155, 2024). "Our study delved into the expression pattern of AURKB in order to assess its significance, genetic alterations and epigenetic modifications in the context of pan‐cancer diagnosis and prognosis." (PMID 38898693, 2024). "In this study, the TIMER 2.0 database was employed to analyse the correlation between AURKB expression and the levels of immune cell infiltration in various cancers." (PMID 38898693, 2024). "In recent years, many studies have reported that AURKB can affect the occurrence and progression of many tumors, and AURKB inhibitors can also inhibit the proliferation of cancer cells." (PMID 38396874, 2024). "Beyond the 33 typical cancers, AURKB displays notable expression in various rare tumours, suggesting a potential association with an unfavourable prognosis." (PMID 38898693, 2024). "As expected, the results revealed that AURKB expression was significantly up-regulated in BC tissues compared to normal tissues adjacent to the cancer, at both mRNA and protein levels." (PMID 38515112, 2024). "In the case of the ALT low TEL high phenotype, we observed that the AURKB gene was upregulated in 11 cancer types." (PMID 38763334, 2024). "Accumulated evidence demonstrates that AURKB is overexpressed in various tumors, contributing to the development and progression of malignant tumors." (PMID 38441546, 2024). "Here, we will focus on the AurkA family member, and we direct the reader to recent reviews for an updated view of AurkB in cancer and as a therapeutic target." (PMID 39195284, 2024). "While the oncogenic potential of AurkA has been proposed since its first identification in human cells, the link between AurkB and cancer was initially less explored." (PMID 39195284, 2024). "This study identified that Aurora kinase B (AurB), a cellular protein that is upregulated in human cancers, is a bona fide interacting partner of HPVE6." (PMID 37173932, 2023). "AURKB depletion has proven beneficial in decreasing tumor progression and resensitizing cancer cells to chemotherapy and target therapy." (PMID 37079315, 2023). "We also demonstrate that cancer cell lines refractory to AURKB kinase inhibitors are sensitive to LXY18." (PMID 37903144, 2023). "By modulating mRNA levels of AURKB, KDM5D promoted the generation of platinum-tolerant persister cells in vitro, leading to the identification of the KDM5D/AURKB axis, which regulates cancer stemness and drug tolerance of HNSCC." (PMID 36982384, 2023). "In this report, we identify for the first time that E6 proteins from cancer-causing HPV types (HPV16 and HPV18) interact with a cell cycle modulator, Aurora kinase B (AurB)." (PMID 37173932, 2023). "TTK has been described to activate AURKB through the phosphorylation of borealin during chromosome alignment and, consequently, treatment of cancer cells with TTKi leads to the inhibition of AURKB, as evidenced by a decrease in phosphor-histone H3 levels." (PMID 37443114, 2023). "The downregulation of ALDH1A3 in response to KDM5D silencing also suggested the role of the KDM5D/AURKB axis in modulating ALDH1A3-mediated cancer stemness, platinum tolerance, and transition towards the quiescent state of HNSCC cells." (PMID 36982384, 2023). "Highly selective inhibitors for AURKB, including hesperadin and barasertib, significantly inhibited human breast, prostate, lung, colon, and blood cancer cell proliferation in vitro and in vivo." (PMID 37079315, 2023).